MIR34C (microRNA 34c)
Synonyms: hsa-mir-34c; MIRN34C; miRNA34C; mir-34c
Gene: MicroRNA gene on chromosome 11 (111,513,439 to 111,513,515, forward strand). Ensembl gene ENSG00000207562.
Pathways (Reactome):
Signal Transduction: MAPK6/MAPK4 signaling; Pre-NOTCH Transcription and Translation
Immune System: Regulation of PD-L1(CD274) translation
Homologues: Orthologues: chimpanzee ptr-mir-34c (100% identical), guinea pig MIR34C (99% identical), macaque mml-mir-34c (97% identical), mouse Mir34c (97% identical), pig ssc-mir-34c-1 (96% identical), zebrafish mir34c (66% identical), Caenorhabditis elegans cel-mir-34 (56% identical), Drosophila melanogaster mir-34 (49% identical). Paralogues in human: MIR34B (65% identical), MIR34A (45% identical).
Diseases named in the same sentence as MIR34C in open-access papers:
MIR34C is named in the same sentence as 2 diseases in open-access papers, as found by Europe PMC text mining. Sharing a sentence is not in itself a finding about the gene and the disease. The quoted sentences say what the papers report.
tumor (2 papers, 2016 to 2021). "Taken together, these results suggest that various molecular mechanisms concur to MYC activity in O1 tumours: genomic alterations, hypomethylation and down-regulation of its silencers mir34b and mir34c through hypermethylation of their promoter region." (PMID 27090007, 2016).
cancer (1 paper, 2021). A tumor composed of atypical neoplastic, often pleomorphic cells that invade other tissues. "Pan-cancer analysis showed that MIR129-2, MIR149, MIR152, MIR150, MIR34B, and MIR34C were downregulated in at least four types of cancer, and MIR150 had a protective role against death in most types of cancer." (PMID 33403044, 2021).